DDIT4 (DNA damage inducible transcript 4)
Diseases named in the same sentence as DDIT4 in open-access papers (continued):
Sharing a sentence is not in itself a finding about the gene and the disease.
non-small cell lung carcinoma (3 papers, 2021 to 2022). A group of at least three distinct histological types of lung cancer, including non-small cell squamous cell carcinoma, adenocarcinoma, and large cell carcinoma. "Nevertheless, one gene found significantly altered upon JIB-04 treatment (DDIT4,DNA damage-inducible transcript 4 protein) was also upregulated in H358 (non-small cell lung cancer cells)." (PMID 34996497, 2022). "In summary, our study demonstrated that DDIT4 is an independent predictor of overall survival in LUAD and has potential as a prognostic biomarker for non-small cell lung cancer in the future." (PMID 34659532, 2021).
oral squamous cell carcinoma (3 papers, 2021 to 2025). "DDIT4 has also been discovered as a downstream target of phenformin, which promotes autophagic and apoptotic cell death to suppress the growth of oral squamous cell carcinoma." (PMID 40584831, 2025).
sarcoidosis (3 papers, 2020 to 2024). Sarcoidosis is a multisystemic disorder of unknown cause characterized by the formation of immune granulomas in involved organs. "Interestingly, this effect is mediated by DDIT4, a gene we found mutated in some sarcoidosis families, also known as REDD1 (regulated in development and DNA damage response 1)." (PMID 32823753, 2020). "In two families with a severe form of sarcoidosis, we demonstrated deleterious mutations in DDIT4 (DNA damage inducible transcript 4 gene), also called Rtp801, encoding a factor that turns off the metabolic activity triggered by mTOR by stabilizing the TSC1–TSC2 inhibitory complex." (PMID 32823753, 2020). "Sarcoidosis unique upregulated DEGs in response to LPS were FOXP1 (Forkhead Box P1), DDIT4 (DNA Damage Inducible Transcript 4), and IL7R, and unique downregulated DEGs in sarcoidosis were PYCARD (Caspase Recruitment Domain-Containing Protein 5), CD4, and PLD3 (Phospholipase D Family Member 3)." (PMID 39284999, 2024).
bladder cancer (2 papers, 2016 to 2020). "Furthermore, GO enrichment analysis suggested that the genes related to DDIT4 expression were mainly concentrated in "acute and chronic myeloid leukaemia," "bladder cancer," "hedgehog signalling pathway," "endometrial cancer," and "basal cell carcinoma" signalling pathways." (PMID 31755224, 2020).
chronic myeloid leukaemia (2 papers, 2020 to 2024). "Gene Ontology (GO) enrichment analysis showed that the genes related to DDIT4 expression were mainly concentrated in the acute and chronic myeloid leukaemia signalling pathways." (PMID 31755224, 2020).
cognitive decline (2 papers, 2021 to 2025). "These high-risk genes dysregulated in more than one cell type, such as IGF1R, DDIT4, and CST3, may be potential targets for delaying the onset of cognitive decline and neurodegenerative diseases in the elderly." (PMID 40036868, 2025).
colitis (2 papers, 2025). Inflammation of the colon. "TSG-6 has been described as an anti-inflammatory mediator with therapeutic potential in colitis, whereas DDIT4 and ISG15 are stress- and inflammation-related factors." (PMID 41354832, 2025). "We further found that in A. shahii As360-treated colitis mice, the expression of mtor and Nlrp3 genes was reduced while the expression of mTOR inhibitor gene Ddit4 was increased." (PMID 39936902, 2025).
endometrial cancer (2 papers, 2020 to 2025). Primary or metastatic malignant neoplasm involving the endometrium (mucous membrane that lines the endometrial cavity). "To determine whether similar effects occur in endometrial cancer, we treated HEC-1A, RL95-2, and ECC-1 cells with baicalein at concentrations ranging from 2.5 to 80 μM for various durations and analyzed the expression of DDIT4 and IRF-1." (PMID 41303544, 2025).
gastric adenocarcinoma (2 papers, 2017 to 2018). "In addition, univariate survival analysis revealed that DDIT4 did not exhibit statistically significant associations with GC patient survival, which is consistent with TCGA analysis for gastric adenocarcinoma." (PMID 29976242, 2018). "However, analysis of the data downloaded from The Cancer Genome Atlas (TCGA) for gastric adenocarcinoma did not reveal differences in survival when comparing two groups with low and high DDIT4 expression (P-value in the log rank test of 0.999)." (PMID 29976242, 2018). "However, the analysis of the data downloaded from the TCGA for gastric adenocarcinoma evidenced not differences in survival when group of patients was split into two groups according to DDIT4 expression (P-value in the logrank test of 0.999)." (PMID 28484222, 2017).
multiple sclerosis (2 papers, 2019 to 2021). A progressive autoimmune disorder affecting the central nervous system resulting in demyelination. "Microarray data from PBMCs of multiple sclerosis (MS) patients revealed that DNA-damage inducible transcript 4 (DDIT4) and the lncRNA DDIT4 (lncDDIT4) are upregulated in Th17 cells compared to other T cell subsets." (PMID 31336952, 2019).
myocardial infarction (2 papers, 2022 to 2023). Gross necrosis of the myocardium, as a result of interruption of the blood supply to the area, as in coronary thrombosis. "Recent research suggests that miR-101-attenuated myocardial infarction (MI)-induced injury by targeting DNA damage-inducible factor 4 (DDIT4) to regulate autophagy, indicating that miR-101 or DDIT4 may be potential therapeutic targets for heart injury and may play a role in apoptosis." (PMID 37229230, 2023).
osteoarthritis (2 papers, 2019 to 2025). A noninflammatory degenerative joint disease occurring chiefly in older persons, characterized by degeneration of the articular cartilage, hypertrophy of bone at the margins and changes in the synovial membrane. "The RT‐qPCR further confirmed that PFKFB4 and DDIT4 expression at the mRNA level was lower in osteoarthritis cartilage tissue than in normal cartilage tissues." (PMID 39846237, 2025).
osteoporosis (2 papers, 2019 to 2025). A condition of reduced bone mass, with decreased cortical thickness and a decrease in the number and size of the trabeculae of cancellous bone (but normal chemical composition), resulting in increased fracture incidence. "Results revealed significant differential expressions of DDIT4, FOXO1, NFKBIA, PGK1, and STAT3 in the osteoporosis model." (PMID 41282482, 2025).
pancreas carcinomas (2 papers, 2020 to 2023). "Phosphorylated UPF1 then drives the degradation of the DDIT4 mRNA (to which DDIT4-AS1 is the antisense) and the activation of the mTOR pathway on the basis of stemness and chemosensitivity of pancreatic carcinoma cells." (PMID 36768150, 2023).
renal cell carcinoma (2 papers, 2014 to 2015). "DDIT4 encodes DNA damage-inducible transcript 4, also known as REDD1, which is a negative regulator of mammalian target of rapamycin (mTOR) and a possible tumor suppressor in renal cell carcinoma." (PMID 24498386, 2014).
steatosis (2 papers, 2021 to 2023). Increased lipid within the cytoplasm of cells. "In addition, quantification of liver triglyceride, cholesterol, and hydroxylproline contents all pointed to amelioration of steatosis as a result of DDIT4 knockdown." (PMID 34310076, 2021).
Stroke (2 papers, 2016 to 2026). Sudden impairment of blood flow to a part of the brain due to occlusion or rupture of an artery to the brain. "The targetgenes of miR-181b, such as DDIT4 and Kank1, were also found to be related to stroke." (PMID 26830013, 2016).
adenoma (1 paper, 2025). A neoplasm arising from the epithelium. "For subsequent timepoints post-TGF-β1, DEGs were mainly observed in Smad4+/+ adenoma organoids and included Skil, Junb, Serpine 1, Ddit4 and Id1." (PMID 40348815, 2025).
aging (1 paper, 2022). A developmental process that is a deterioration and loss of function over time. "It has been reported that DDIT4 is associated with senescence, and our previous studies demonstrated that HDAC4 might be a key regulator of skin aging." (PMID 35680564, 2022).
anemia (1 paper, 2025). A reduction in the number of red blood cells, the amount of hemoglobin, and/or the volume of packed red blood cells. "In contrast, models of IDA and phlebotomy-induced anemia indicate diminished mTOR signaling, partially via changes in the hypoxia-sensitive DDIT4/REDD1 pathway." (PMID 40863165, 2025).
aneurysm (1 paper, 2024). Bulging or ballooning in an area of an artery secondary to arterial wall weakening. "Nevertheless, MT1G and DDIT4 give rise to further thinking about the pathogenesis of ruptured aneurysms." (PMID 38728466, 2024).
Arthritis (1 paper, 2022). Inflammation of a joint. "Therefore, our analyses also dictate for previously underexplored gene targets in arthritis, such as Rspo3 (effector molecule of WNT pathway) or Ddit4 (hypoxia-induced, regulator of mTOR1 activity)." (PMID 35879783, 2022).
autism spectrum disorder (1 paper, 2025). A spectrum of developmental disorders that includes autism, and Asperger syndrome. "Moreover, excessive DDIT4 expression has been shown to be detrimental to neurodevelopment, and its expression has been correlated to pathophysiology of autism spectrum disorder (ASD)." (PMID 41153391, 2025).
bone metastasis (1 paper, 2024). Transfer of a neoplasm from its primary site to bones. "Decreased FTO expression was an independent indicator of worse survival, and the level of DDIT4 was considerably elevated in patients with bone metastasis." (PMID 38384328, 2024). "However, because of limited clinical data, the relationship between DDIT4 expression and bone metastasis could not be adequately investigated in this study." (PMID 38384328, 2024).
brucellosis (1 paper, 2022). Brucellosis is a bacterial infection that spreads from animals to people via unpasteurized dairy products or by exposure to contaminated animal products or infected animals. "Treatment of brucellosis led to increased expression of several genes related to autophagy machinery in PMNs, including DDIT4/REDD1 encoding a key regulator of autophagy-mediated NET formation." (PMID 35979363, 2022).
cerebral infarction (1 paper, 2021). An ischemic condition of the brain, producing a persistent focal neurological deficit in the area of distribution of the cerebral arteries. "Overexpressed Smurf2 or downregulated YY1, HIF1α, or DDIT4 reduced the volume of cerebral infarction and apoptosis in MCAO mice, while enhancing cell viability and reducing apoptosis and lactate dehydrogenase leakage in OGD-treated neurons." (PMID 33722608, 2021). "TTC staining exhibited that after treatment with oe-Smurf2, cerebral infarction volume was reduced in MCAO mice, which was neutralized by overexpressing DDIT4 (p < 0.05)." (PMID 33722608, 2021).
colorectal tumor (1 paper, 2022). "Another study indicated that the ATF4 pathway was activated, and the DDIT4 was upregulated to restrict mTOR and promote autophagy after inhibiting glutamine decomposition in colorectal tumor cells." (PMID 35013120, 2022).
cutaneous squamous cell carcinoma (1 paper, 2022). "1,25-(OH)2D3 also induces autophagy through the mTOR pathway in Pfeiffer diffuse large B lymphoma cells and is mediated by activation of DNA damage-inducible transcript 4 (DDIT4), in cutaneous squamous cell carcinoma cells." (PMID 35406059, 2022).
giant cell arteritis (1 paper, 2025). "DDIT4 and ARHGAP15 have significant causal effects on giant cell arteritis risk." (PMID 39762453, 2025).
ischemic heart disease (1 paper, 2021). "However, lots of DEGs were not previously reported in the investigation of VNS, such as CD163, CD48, DDit4, and ADAMTS1, which have been demonstrated close association with ischemic heart disease." (PMID 33981734, 2021).
laryngeal squamous cell carcinoma (1 paper, 2021). A squamous cell carcinoma that arises from the larynx. "Similar findings have been reported in laryngeal squamous cell carcinomas for other binomial LncRNA/mRNA transcripts, such as: NR_003919/PIK3R1, NR_027340/ITGB1, MIR31HG/HIF1A, and SOX2‐OT/DDIT4." (PMID 33433063, 2021).
nasopharyngeal carcinoma (1 paper, 2023). A carcinoma arising from the nasopharyngeal epithelium. "Previous literature has revealed that DDIT4 expression was much higher in nasopharyngeal carcinoma (NPC) and HNSCC tissues than in adjacent tissues." (PMID 36702843, 2023).
Nocardia infection (1 paper, 2022). "In our study, we found that the expression of DDIT4 was upregulated, which suggested that this gene might participate in lung inflammation induced by Nocardia infection." (PMID 36352407, 2022).
pancreatic adenocarcinoma (1 paper, 2023). "Based on the analysis conducted on the TCGA database through GEPIA2, few changes were observed in the mRNA levels of DDIT4 in pancreatic adenocarcinoma (PAAD) tissue samples compared to the normal tissues (P < 0.05)." (PMID 37938616, 2023).
pancreatic ductal adenocarcinoma (1 paper, 2023). An infiltrating adenocarcinoma that arises from the epithelial cells of the pancreas. "A statistically significant association was detected between a high level of nuclear expression of DDIT4 protein, and lymphovascular invasion (P = 0.025), as well as advanced TNM stage (P = 0.034) pancreatic ductal adenocarcinoma (PDAC) and in pancreatic neuroendocrine tumor (PNET), respectively." (PMID 37938616, 2023).
parasite (1 paper, 2022). "Though the importance of CCL4 and DDIT4 in immune response has been known, their function in L. crocea is relatively rarely reported, especially after parasite infection." (PMID 35287569, 2022).
parasite infections (1 paper, 2022). "Importantly, we have identified candidate innate immunity-related genes, including CCL4 and DDIT4, that may play key roles in the anti-inflammatory response during parasite infections." (PMID 35287569, 2022).
promyelocytic leukemia (1 paper, 2020). "In another report, the dysregulation of basal DDIT4 gene expression in several cancer types (e.g. lung, breast, prostate) can be altered by promyelocytic leukemia (PML) and lead to mTOR activation and cancer progression." (PMID 32497068, 2020).
schizophrenia (1 paper, 2023). A major psychotic disorder characterized by abnormalities in the perception or expression of reality. "Among the 7 DEGs, the TNC gene was the only gene that decreased with schizophrenia and showed a positive correlation with PI (16:0/20:4), while the other 6 DEGs (COL1A2, COL6A2, DDIT4, FGF17, GNB3, and PDGFRB) increased with schizophrenia and showed a negative correlation with PI (16:0 /20:4)." (PMID 37143779, 2023).
serous ovarian cancer (1 paper, 2018). "Both DDIT4 and p-Akt expressions were significantly higher in patients with serous ovarian cancer and late FIGO stage; while only DDIT4 expression was significantly higher in ascites formation and only p-Akt expression was significantly histological grade and chemoresistance." (PMID 29707520, 2018).
Splenomegaly (1 paper, 2025). Abnormal increased size of the spleen. "The mice in the Ddit4+/+ group displayed a severe splenomegaly, while the AE9a‐Ddit4−/− cell transplanted mice did not." (PMID 40621878, 2025).
stomach tumor (1 paper, 2020). "Conversely, DDIT4, NDRG1, and CHAC1 showed lower levels in stomach tumor tissues than that in normal tissues." (PMID 32457731, 2020).
uveal melanoma (1 paper, 2024). A melanoma derived from melanocytes of the uveal tract. "Physiologically, we demonstrate that DDIT4 overexpression or pharmacological inhibition of mTORC1 effectively abrogates the oncogenic potential of serum-unresponsive uveal melanoma cells, which commonly originate from mutations in G protein-coupled receptor (GPCR)-encoding genes." (PMID 39349825, 2024). "DDIT4 was sufficient to suppress the translation and transformative potential of uveal melanoma cells, which are often serum unresponsive due to G protein mutations." (PMID 39349825, 2024).
tumor (132 papers, 2009 to 2026). "Our findings further demonstrate that resistance to ER stress-induced apoptosis in multicellular tumor spheroids (MCTS) is associated with constitutive expression of REDD1/DDIT4 and diminished mTORC1 activity." (PMID 41904147, 2026). "The tumour suppressor gene Cdkn2a,80 DNA damage repair gene Ddit4,81 oncogene Myc,82 and metabolism‐associated gene Pkm83 exhibited markedly heightened expression levels in these tumour cells." (PMID 40887856, 2025). "The expression of NDRG1 (N-Myc downstream regulated gene 4) and DDIT4 (DNA damage–inducible transcript 4), both of which are also implicated in tumor growth, was downregulated by both imeglimin and metformin." (PMID 36639407, 2023). "Conversely, high membranous expression of DDIT4 was associated with less aggressive tumor behavior in patients with PDAC." (PMID 37938616, 2023). "This article only captured the tumor tissue at a point in time and through the comprehensive analysis of the DDIT4 gene mutations in multiple tumor samples, but the evidence is indirect." (PMID 34007269, 2021). "The results of Pearson’s chi-square test revealed that nuclear expression of DDIT4 in terms of intensity of staining (P = 0.031) and H-score (P = 0.009) had a significant association with tumor differentiation." (PMID 34211002, 2021). "Our findings indicated higher nuclear expression of DDIT4 was significantly associated with more aggressive tumor behavior and more advanced stage of disease in the patients with CRC." (PMID 34211002, 2021). "Subcutaneous injection into nude mice of MEFs containing constitutively activated Akt results in slow-growing tumors, and the additional deletion of Ddit4 causes much more rapid tumor growth." (PMID 19370158, 2009). "However, the mechanisms underlying how DDIT4 is involved in tumor immune regulation remain to be fully elucidated." (PMID 40900790, 2025). "Notably, higher levels of DDIT4 nuclear expression have been associated with more aggressive tumor behavior." (PMID 37938616, 2023). "Furthermore, higher nuclear expression of DDIT4 was found to be significantly associated with the reduced tumor differentiation and advanced TNM stages (all, P = 0.009)." (PMID 34211002, 2021). "The transient elevation of DDIT4 expression might reduce tumor growth, while high and constitutive expression was linked with poor prognosis in diverse hematologic and solid tumors." (PMID 35096011, 2021). "Additionally, DDIT4 is associated with the cell invasion and migration of ovarian epithelial cells, facilitating the expression of autophagy-related proteins and inhibiting tumor cell apoptosis." (PMID 38339228, 2024). "DDIT4 is a stress-response protein whose main function is to inhibit mTOR under stressful conditions.DDIT4 is considered an oncogene, and its overexpression is significantly associated with poorer prognosis in tumor patients (Tirado-Hurtado, Fajardo & Pinto, 2018)." (PMID 34434660, 2021). "This comprehensive analysis aims to establish a theoretical foundation for considering DDIT4 as a potential therapeutic target in tumor immunotherapy." (PMID 40900790, 2025). "Extensive research has demonstrated that DDIT4 expression is aberrantly elevated in various malignancies, where it exhibits context-dependent roles in either tumor promotion or suppression." (PMID 40900790, 2025). "It has been reported that sustained DDIT4 overexpression, inhibits mTORC1, but activates mTORC2-mediated Akt phosphorylation, a key survival signal, ultimately promoting tumor cell survival and chemoresistance." (PMID 41286896, 2025). "The more detailed regulatory mechanisms through which inhibitors such as DDIT4, suppress mTORC1 complex and subsequently modulate B cells to either enhance or suppress tumor immunity require further elucidation." (PMID 40900790, 2025).